CXCR4 (C-X-C motif chemokine receptor 4)
Diseases named in the same sentence as CXCR4 in open-access papers (continued):
Sharing a sentence is not in itself a finding about the gene and the disease.
tumor (continued). "In reference to percentage of elevated concentrations, the combined analysis of CXCR4 and the well-established tumor marker may be more useful in the diagnosis of PC when compared to the measurement of a single biomarker." (PMID 32867211, 2020). "Patients with a high CXCR4 expression have a lower tumor purity, which can lead to poor survival." (PMID 32306562, 2020). "Going deeper into the mechanism, T22-PE24-H6 internalizes in CXCR4+ tumor cells by endocytosis." (PMID 32373205, 2020). "Furthermore, a positron emission tomography (PET)/CT scan using 18F-FDG was conducted on three mice showing reduction in tracer uptake in RT-CT, and in Pep R treated tumors, consistent with reduced tumor metabolism as previously reported for CXCR4 antagonists." (PMID 32708431, 2020). "Blocking CXCL12/CXCR4 signaling between pancreatic cancer cells and CAFs could attenuate RT-induced tumor cell invasion." (PMID 33050580, 2020). "Notably, CAF depletion through genetic ablation or a CXCR4 inhibitor reduced tumor volume in autochthonous KPC mice, and synergized with PD-L1 blockade." (PMID 33584701, 2020). "In addition, CXCL12 expression was barely detectable in the primary tumor stromal tissue, but was strongly expressed in metastatic lymph node stroma, illustrating the CXCR4/CXCL12 axis as a highly plausible mechanism for metastatic spread in this cancer." (PMID 32296435, 2020). "This apparent conundrum may reflect the fact that CXCR7 can heterodimerize with CXCR4 and that loss of CXCR7 may disrupt the balance between oncogenic CXCR4/CXCR7 heterodimers and tumor suppressor homodimers." (PMID 33363463, 2020). "Moreover, CXCR4 is highly expressed in the endothelial cells of large vessels in tumor stroma, indicating that the CXCL12/CXCR4 signaling plays a vital role in tumor angiogenesis." (PMID 33363463, 2020). "Thus, there is some evidence that Cxcr4 signalling recruits macrophages and has a pro-tumour effect during early stage tumourigenesis in mammalian models." (PMID 32325966, 2020). "Taken together, these observations support the proposal that CXCR4 may be a useful biomarker for predicting tumor progression." (PMID 32368286, 2020). "The hypothesis that tumor cells use the SDF-1/CXCR4 axis to hone to the osteoblastic niche in bone is supported by the finding that both, newly and established metastases are anchored in the bone marrow by SDF-1/CXCR4 interactions." (PMID 32232008, 2020). "Moreover, the CXCL12/CXCR4 cascade affects both immune and stromal cells, creating tumor-supporting microenvironment." (PMID 33096815, 2020). "Cxcr4b is highly expressed on zebrafish neutrophils and together with its ligand Cxcl2a, it facilitates tumor angiogenesis and dissemination into different tissues by attracting malignant Cxcr4-expressing cells into healthy organs and tissues where ligand can be found." (PMID 32161595, 2020). "Inhibition of the CXCR4-CXCL12 axis, on the other hand, can sensitize cancer cells to chemotherapy or radiotherapy by inhibiting the interaction between the CXCR4-expressing tumor cells and stromal cells, resulting in decreased cancer cell protection by the CXCL12 releasing stromal cells." (PMID 31802362, 2020). "We used available GC patient data from the Gene Expression Omnibus (GEO) and The Cancer Genome Atlas (TCGA), and investigated the role of CXCR4 in GC in relation to the clinical characteristics, tumor purity, immune infiltration, TMB, CYT, survival, and other parameters." (PMID 32306562, 2020). "Herein, the expression of miR-21 and CXCR4 was increased in tumor tissues and cell lines." (PMID 33123586, 2020). "Significantly, CD164 regulates CXCR4 function in different tumor types." (PMID 32719743, 2020). "Moreover, Plerixafor inhibition of CXCL12/CXCR4 axis can reverse the tumor-promoting signals of stromal cells, increasing the spontaneous apoptosis rate of tumor cells and enhancing their response to chemotherapy." (PMID 32784523, 2020).
tumor (continued). "Thus, curcumin and luteolin impair the migratory activity in tumor cells by the repression of the CXCL12/CXCR4 biological axis, as a consequence of the downregulation of MMP-9 by luteolin." (PMID 33195200, 2020). "Growing evidence has shown that the SDF-1α/CXCR4 axis could regulate the activities of tumor cells and play a key part in modulating the interaction of CXCR4+ tumor cells and SDF-1α-expressing organs." (PMID 32344892, 2020). "Finally, the in vivo anticancer efficacy study demonstrated that the SSTR2/CXCR4 dual-targeted EV-Ver-A/DM1 is more effective to inhibit NE tumor growth than the single targeting and single drug." (PMID 33187322, 2020). "Recent in vivo preclinical studies indicated that the combination of small molecule CXCR4 antagonists and anti-PD-1 antibodies significantly enhanced anti-tumor effects compared with single-agent administration in syngeneic murine models of ovarian cancer, colon cancer, and melanoma." (PMID 32972006, 2020). "In addition, tumor-bearing mice were treated with the CXCR4 antagonist AMD3100 (Plerixafor®) to inhibit the chemotaxis mediated by the CXCR4 receptor." (PMID 31802362, 2020). "Ionizing radiation was shown to up-regulate CXCL12/CXCR4 signalling in various tumour entities." (PMID 31959787, 2020). "Moreover, many reports indicate that binding of CXCL12 to CXCR4 on tumor cells of various types enhances their proliferation, both in vitro and in vivo, either via MAPK or PI3K/Akt pathways." (PMID 32983169, 2020). "A biodistribution study revealed that 211At-CXCR4 mAb as well as 125I-CXCR4 mAb showed the highest tumor uptake and the highest tumor-to-muscle ratio at 6 h, which agreed with the physical half-life of 211At, although the precise biological behavior from 6 to 24 h was not evaluated in this study." (PMID 32321944, 2020). "We found that Curcumin treatment seemed to reduce CXCR4 levels in grafted tumor." (PMID 30844765, 2019). "CXCR4 expression was higher in tumour cell lines than in normal bone marrow haematopoietic cells." (PMID 30792442, 2019). "Notably CXCR4 has a well-established role in tumor angiogenesis as well, and is being actively pursued as a therapeutic target." (PMID 31105685, 2019). "In contrast to that observed in immunodeficient mice, tumor growth was not significantly blocked after CXCR4 abrogation, or after AMD3100 treatment, suggesting that the effect of CXCR4 inhibition on tumor growth may be tumor microenvironment-dependent." (PMID 30874597, 2019). "The overall goal of this study was to determine whether expansion of CD103+ dendritic cells by the virally delivered CXCR4 antagonist augments overall survival and in situ boosting with a tumor antigen peptide-based vaccine." (PMID 31384667, 2019). "Similarly, small molecules blocking CXCR4 activation modulate the tumour/stem cell niche as shown by the CXCR4 antagonist plerixafor (AMD3100)." (PMID 31877673, 2019). "Furthermore, downregulation of the Notch1 pathway by shRNA and MK0752 significantly inhibited the PI3K/AKT/mTOR signaling pathway via the decreased expression of CXCR4 in GICs, and weakened the self-renewal, invasion and tumor growth ability of GICs." (PMID 31382985, 2019). "The CXCR4/SDF-1 axis is involved in tumor growth and metastasis of TNBC." (PMID 32047724, 2019). "In the present study, we first aimed to clarify which type of cells could be positive with CXCR4 in OSCC and whereby focused on CXCR4/CD34 double-positive tumor vasculatures in clinical specimens of OSCC." (PMID 31336612, 2019). "The CXCR4 inhibitor AMD3100 can counteract this tumor promoting effect." (PMID 31561620, 2019). "CXCR4 represents an attracting molecule that could at the same time be able to inform about the tumor infiltration and its immune-environmental counterpart and could select patients suitable to CXCR4-directed therapies." (PMID 31323969, 2019). "Anti-CXCR4 ADC rather eliminates tumour cells, thereby overcoming such limitation." (PMID 30792442, 2019).
tumor (continued). "Interestingly, shIF1 cells reveal significant increased expression of the CXC chemokine receptor 4 (CXCR4), which is involved in the inhibition of the activation and proliferation of NK cells by tumor cells." (PMID 31861681, 2019). "Therefore, overexpression of CXCR4 is a critical factor for tumor progression and metastasis via regulating AKT signaling pathway." (PMID 30430424, 2019). "We also tested whether medium and low cell binding ADCs 553 and 556 were able to compete with CXCL12 for binding to CXCR4 in CXCR4Low tumours." (PMID 30792442, 2019). "Some of the more well described targets are SPRED1, p85β, and PI3KR2 governing vascular integrity, VEGF-A regulating AKT-pathway signaling, CXCR4 and IRS-1 involved in CRC cell proliferation and migration, and KRAS impacting on the viability of the mutated tumor cells." (PMID 35582589, 2019). "Altogether, metabolic immune suppression by the tumor microenvironment and enhanced CXCR4 signaling could be involved in lessening immune surveillance of shIF1 carcinomas." (PMID 31861681, 2019). "CXCR4 is mainly expressed in the tumor cells and its ligand in bone marrow endothelial (BME) cells." (PMID 31877673, 2019). "Hence, blockade of CXCR4 using the FDA-approved agent Plerixafor (AMD3100) inhibited anti-VEGFR2 therapy-induced tumor infiltration of neutrophils and Ly6Clow monocytes." (PMID 31616408, 2019). "CXCR4 signaling is critical for determining the site of tumor cell metastasis." (PMID 30177838, 2019). "Taken the existing knowledge of CXCR4 as a key player in tumor cell adhesion and sphere formation, we found it worth to examine the effect of its inhibition on spheroid formation under s-μg, particularly as its gene expression was significantly upregulated in the spheroids." (PMID 31810195, 2019). "CXCL12 signaling via CXCR4 is critical for the regulation of hematologic tumor cell adhesion." (PMID 30787933, 2019). "We next hypothesized that the TAITN triggered by CXCR4 antagonism could also induce tumor hypoxia inasmuch as angiogenic inhibition." (PMID 31336612, 2019). "A similar mechanism is mediated by tumor-expressed CXCR4 and CXCL12 expressed in LECs and LNs." (PMID 31105685, 2019). "CXCR4 is a well-studied receptor in stem cells and cancer models and most studies have evaluated its expression on the tumor cells." (PMID 31663852, 2019). "To create an alternative parameter for CXCR4 affinity that more closely correlated to tumor uptake in vivo, we titrated the tumor uptake of [68Ga]Pentixafor, [18F]RPS-534, [18F]RPS-544, and [18F]RPS-547 in μPET/CT images by co-injection of increasing masses of AMD-3100." (PMID 31022852, 2019). "We next examined the expression and distribution of CD34 and CXCR4 in the tumor and stroma areas." (PMID 31336612, 2019). "CXCR4 expression has been also associated with increased angiogenesis, secretion of vascular endothelial cell growth factor (VEGF), interleukin-8 (IL-8), and MMP-9, facilitating tumour invasiveness and metastatic progression in the bone." (PMID 31877673, 2019). "Activation of CXCR4 by CXCL12 has been reported to have pro-tumor activity." (PMID 30873179, 2019). "Through secreting CXCL12, geminin-overexpressing cells recruit these CXCR4+-MSCs into the tumor." (PMID 31844158, 2019). "It was reported that transient disruption of the SDF‐1/CXCR4 axis using CXCR4 blocking antibody blocked the recruitment of bone marrow‐derived cells into the angiogenic sites of tumour tissue, and resulted in an inhibition of accelerated tumour growth." (PMID 30950188, 2019). "Finally, we found that CXCR4, which has been reported to promote NB tumor growth, metastasis and resistance to therapeutics and was therefore chosen in this study as a marker of aggressiveness, was found to be downregulated after PRIMA-1MET exposure." (PMID 30755224, 2019). "In addition, blockade of CXCL-12/CXCR-4 axis prevented the post-sepsis-induced tumor progression, TAM accumulation, and TAM in situ proliferation." (PMID 31805946, 2019).
tumor (continued). "Furthermore, the SDF-1/CXCR4 axis plays decisive roles in tumor progression, including the enhancement of migration and invasion, cancer cell–tumor microenvironment interaction, and angiogenesis." (PMID 31336612, 2019). "Also, the elevated expression of CXCR4 in metastatic lesions correlates with tumor progression and with preferential metastatic sites of the primary tumor." (PMID 31507535, 2019). "We used anti-CXCR4 m17 antibody to specifically detect human CXCR4+ tumour cells." (PMID 30792442, 2019). "Finally, CXCR4 plays a pivotal role in tumor development and metastasis and it is overexpressed in many solid and hematologic cancers." (PMID 30830470, 2019). "Thus, it is known that the SDF-1/CXCR4 axis is involved in tumour metastasis, which plays an important role in the metastasis of digestive system tumours." (PMID 31752959, 2019). "Taken together, these results suggest that mast cells may be induced to migrate into the tumor microenvironment through CXCR4-mediated chemotaxis." (PMID 30808413, 2019). "We next sought to determine whether high CXCR4 expression promotes tumor progression to an invasive phenotype in vivo." (PMID 30678736, 2019). "Since existing TEC in many cases express CXCR4, targeting CXCR4 with a cytotoxic monoclonal antibody (mAb) could lead to tumor vascular disruption and neoplastic necrosis." (PMID 30800123, 2019). "We next asked whether a CXCR4 antagonist AMD3100 could alter the tumor status of OSCC using tumor xenograft mouse model." (PMID 31336612, 2019). "High levels of CXCR4 in tumor endothelial cells could induce tumor angiogenesis, which facilitates tumor metastasis and correlates with poor prognosis of HCC patients." (PMID 31534521, 2019). "Given the critical role of CXCR4 in HCC progression 20, 22, 25, 29 and the most obvious expression-altering gene in TCF12 knockdown cells, we decided to investigate the role and the underlying mechanism of CXCR4 in pro-tumor function of TCF12 in HCC." (PMID 31534521, 2019). "In addition these anti-tumour effects were stronger when compared to subcutaneous 22rv1 tumour suggesting a major role of CXCR4 in the bone microenvironment dependent tumour growth and drug resistance respect to a primary lesion." (PMID 31877673, 2019). "Finally, the first in-human study of 68Ga-CXCR4, targeting chemokine receptor CXCR4, which is frequently overexpressed in various tumor types, showed high lesions’ uptake." (PMID 31480470, 2019). "CXCR4 promotes tumor cell migration toward nerve cells and SDF1 increases NGF expression." (PMID 31921628, 2019). "In addition, a small molecule, partial antagonist of CXCR4, inhibited metastasis formation in different xenograft tumor models, including UM." (PMID 31216772, 2019). "We next hypothesized that CXCR4 antagonism-induced tumor necrosis and hypoxia could be mediated by disorganization of vessels, whereby oxygen and nutrition were limited." (PMID 31336612, 2019). "Also, tumor formation in distal organs was detected in mice that received MMP-26+CXCR4+HepG2 HCC cells, suggesting that MMP-26 plays a role in the EMT of HCC." (PMID 31886121, 2019). "Notably, the anti-CXCR4 antibody used for immunohistochemistry binds to an intracellular epitope and therefore it is unlikely that low detection levels of CXCR4 expression in ADC 713-treated tumours are due to epitope masking by the anti-CXCR4 ADC." (PMID 30792442, 2019). "CXCL12 also stimulates proliferation and survival of CXCR4 positive tumor cells." (PMID 31248118, 2019). "A recent phase I trial in women with advanced HER-2 negative metastatic breast cancer investigated a combination regimen of balixafortide (a peptidic CXCR4 antagonist) and eribulin and demonstrated favorable safety and tolerability as well as promising anti-tumor activity." (PMID 31475113, 2019). "However, CXCR4 acquisition seems important for infiltration of neutrophils into the tumor, at least in a preclinical model of colorectal cancer." (PMID 31616408, 2019).
tumor (continued). "However, contrary to its endogenous and homogeneous expression in haematological cancers, CXCR4 expression in solid tumour cancer cells is ectopic and heterogeneous, mostly observed in cells displaying tumour-initiating and/or metastatic abilities." (PMID 30792442, 2019). "The anti-proliferative effects of GMI-1359 and DTX correlated with decreased size, osteolysis and serum levels of both mTRAP and type I collagen fragment (CTX) in intra-osseous tumours suggesting that the dual CXCR4/E-selectin antagonist was a docetaxel-sensitizing agent for bone metastatic growth." (PMID 31877673, 2019). "Given that all tumor lesions in our cohort demonstrated CXCR4-positivity, CXCR4 could be a promising target for chemokine receptor-directed therapies." (PMID 31245296, 2019). "In models of prostate cancer, inhibition of CXCR4-dependent vascularization delayed tumor growth." (PMID 30813533, 2019). "The apparent CXCR4 affinity of the ligands was relatively low, but tumor uptake was CXCR4-specific." (PMID 31022852, 2019). "IHC results showed that AMD3100 could also impede CXCR4 expression on AGTR1high tumor tissues (1.37 in MOCK vs. 2.14 in AGTR1high vs. 1.38 in AGTR1high+AMD3100)." (PMID 31219799, 2019). "CXCR4 is upregulated by HIF-1α, and the hypoxia–HIF-1α–CXCR4 axis may participate in pathophysiological mechanisms under several conditions ranging from inflammation to tumor angiogenesis and metastasis." (PMID 30177838, 2019). "GAB1 upregulation promotes tumor cell invasion, migration via CXCR4 and tumor growth." (PMID 31024232, 2019). "The chemical and pharmacokinetic properties of [18F]RPS-547 and especially [18F]RPS-534, including high yielding radiosynthesis, high tumor uptake, and good contrast to background, render these radiotracers promising candidates for imaging CXCR4 expression by PET." (PMID 31022852, 2019). "Our study indicated that tumor angiogenesis was inhibited by antagonizing CXCR4, although this anti-angiogenesis approach could result in tumor hypoxia inducing HIF-1α." (PMID 31336612, 2019). "Intravenous injection into mice carrying subcutaneous EGFRvIII-positive GB xenografts resulted in inhibition of tumor growth and extended survival, which was further enhanced by co-expressing the chemokine receptor CXCR4 in the CAR-NK cells for improved tumor homing." (PMID 31798595, 2019). "This has been shown for CXCR4, the chemokine receptor most frequently overexpressed in tumor cells." (PMID 31428099, 2019). "In addition, the CXCR4 expression site in tumor blood vessels was limited to a bifurcation or constricted part of the blood vessels." (PMID 31336612, 2019). "Finally, in dissected tumors from mice that had received Curcumin or control, the protein levels of CXCR4 were quantified by Western blotting, showing that the Curcumin treatment indeed reduced CXCR4 levels in grafted tumor." (PMID 30844765, 2019). "However, due to widespread expression of CXCR4 in haematopoietic cells, on-target, but off-tumour toxicity would remain a concern." (PMID 30792442, 2019). "Indeed, elevated levels of SDF-1/CXCL12 in the TME forms a local concentration gradient along which CXCR4-expressing cells, such as bone marrow-derived mesenchymal stem cells (MSCs) can migrate along, homing to the tumour." (PMID 31861782, 2019). "Considering the detection sensitivity of the applied analytical method, no other MMPs, CXCL12, and CXCR4, associated or overexpressed in tumor recurrence, were found in the AC solid tissues analyzed." (PMID 31191748, 2019). "Indeed, targeting CXCR-4 in several preclinical models, including breast, prostate, and ovarian cancer, was shown to significantly reduce total tumor burden and metastases." (PMID 31805946, 2019). "CXCR4 knockdown in L-CSCs significantly reduced PD/S-SCC growth in immunodeficient mice, but not upon a proficient immune system, suggesting that impact of CXCR4 inhibition on tumor growth may be dependent of tumor microenvironment." (PMID 30874597, 2019).